TWIST1 (twist family bHLH transcription factor 1)
Diseases named in the same sentence as TWIST1 in open-access papers (continued):
Sharing a sentence is not in itself a finding about the gene and the disease.
lung adenocarcinoma (26 papers, 2012 to 2025). A carcinoma that arises from the lung and is characterized by the presence of malignant glandular epithelial cells. "TWIST1-induced increase in the expression of miR-214 is shown to promote epithelial-to-mesenchymal transition and metastasis in lung adenocarcinoma." (PMID 34530740, 2021). "Compared to adjacent tissues, expression of both USP4 and Twist1 proteins were high in biopsy specimens of lung adenocarcinoma patients." (PMID 32549341, 2020). "We further demonstrated that circASPH, which was directly regulated by HMGA2 and Twist1, promoted malignant phenotypes in lung adenocarcinoma by sponging miR-370, and the oncogenic effects of circASPH were HMGA2-dependent." (PMID 32719345, 2020). "The findings that circASPH was upregulated in lung adenocarcinoma tissues, and was directly regulated by HMGA2 and Twist1 prompted us to consider circASPH as an oncogene in lung adenocarcinoma." (PMID 32719345, 2020). "We further examined the clinical correlation between USP4 and Twist1 using tissue microarrays of lung adenocarcinoma." (PMID 32549341, 2020). "It has been reported that Twist1 is critical for oncogene-driven cell proliferation since silencing of Twist1 induces senescence in lung adenocarcinoma cells driven by various oncogenic drivers." (PMID 32549341, 2020). "Here, we found increased SOD-2 expression associated with vimentin, α-SMA, Twist1, and MMP upregulation in AFG1-induced lung adenocarcinoma." (PMID 28801561, 2017). "To further investigate the relation between SOD-2 overexpression and EMT, we examined the well-defined markers of EMT, including E-cadherin, vimentin, α-SMA, and Twist1 in AFG1-induced lung adenocarcinoma." (PMID 28801561, 2017). "We generated two novel autochthonous transgenic mouse models to demonstrate that Twist1 overexpression cooperates with KrasG12D to markedly accelerate the onset of lung adenocarcinoma." (PMID 22654667, 2012). "Moreover, in lung adenocarcinoma, poor prognostic factors of TWIST1 and ZFHX4 are targeted by miR-514a-3p, and ZFHX4 exerts oncogenic functions by regulating TWIST1." (PMID 33766100, 2021). "One example of this is an inducible triple transgenic autochthonous mouse model of lung adenocarcinoma (CCSP-rtTA/tetO-KrasG12D/Twist1-tetO7-luc), which our group has used recently to show the radiosensitizing properties of Hedgehog pathway inhibition on the tumor microenvironment." (PMID 23863691, 2013). "In this work, we tested the hypothesis that TWIST1 and mutated EGFR could similarly cooperate in promoting EMT in lung adenocarcinomas." (PMID 22272264, 2012). "The targeted inactivation of TWIST1 may be an effective pro-senescence therapy for human lung adenocarcinomas." (PMID 22654667, 2012). "Our results illustrate that TWIST1 may be an important target for the treatment of human lung adenocarcinoma." (PMID 22654667, 2012). "We studied a series of consecutive lung adenocarcinoma from Caucasian non-smokers for which surgical frozen samples were available (n = 33) and showed that TWIST1 expression was linked to EGFR mutations (P<0.001), to low CDH1 expression (P<0.05) and low disease free survival (P = 0.044)." (PMID 22272264, 2012). "Neutrophils also secrete transforming growth factor (TGF)-beta, upregulating transcription factors such as Snail1/2, Zeb1/2, and Twist1, which drive EMT and promote lung adenocarcinoma development." (PMID 40870429, 2025). "Recent studies by our research group have revealed that the overexpression of RUNX2 in lung adenocarcinoma is involved in epithelial-mesenchymal transition through transcriptional regulation of the VIMENTIN, TWIST1, and SNAIL1 genes." (PMID 36510562, 2022). "In this study, we constructed a mRNA-mRNA related ceRNET of lung adenocarcinoma (LUAD) and identified the highlighted TWIST1-centered ceRNET, which recruits SLC12A5 and ZFHX4 as its ceRNAs." (PMID 31645542, 2019).
lung adenocarcinoma (continued). "AFG1-induced lung adenocarcinoma expressed high levels of vimentin, α-SMA, and Twist1 in cancer cells." (PMID 28801561, 2017). "Western blot results showed elevated expression of vimentin, α-SMA, and Twist1, while lower expression of E-cadherin, in the lung tissues of mice with AFG1-induced lung adenocarcinoma." (PMID 28801561, 2017). "Expression of TWIST1, mesenchymal (CDH2, VIM, SNAI1, ZEB1) and epithelial (CDH1, JUP) markers in lung adenocarcinoma cell lines." (PMID 22272264, 2012). "Interestingly, among the other defective pathways in the MPM group, one (R-HSA-8941326) affects RUNX2, the master gene in osteogenesis, which has been shown to increase expression of EMT genes (included in R-HSA-8941326) vimentin, TWIST1 and SNAIL1 in lung adenocarcinoma cells." (PMID 36362413, 2022).
pulmonary fibrosis (24 papers, 2010 to 2025). Chronic progressive interstitial lung disorder characterized by the replacement of the lung tissue by connective tissue, leading to progressive dyspnea, respiratory failure, or right heart failure. "In line with our findings, TWIST1 has also been implicated in other fibrotic diseases, such as pulmonary fibrosis and renal fibrosis." (PMID 39042469, 2024). "TWIST1 is involved in the obesity- and angiogenesis-associated diseases such as pulmonary fibrosis, pulmonary hypertension, and atherosclerosis." (PMID 39479393, 2024). "Sustained activation of the Twist1-Prrx1-TNC PFL reproduces fibrotic nodules similar to idiopathic pulmonary fibrosis in vivo and is implicated in fibrotic disease and cancer stroma." (PMID 30069061, 2018). "Twist1 is also involved in pulmonary fibrosis and endotoxin-induced decreases in vascular integrity." (PMID 39479393, 2024). "We next addressed how the expression of EMT-inducing transcription factors, Snai1, Snai2, Twist1, Twist2, Zeb1 and Zeb2, changed in the lungs from WT and Plaur-/- mice at Day 7, 14, 21 and 28 after bleomycin-induced pulmonary fibrosis." (PMID 36674896, 2023). "In this study, PNS reversed the progression of pulmonary fibrosis by blocking the expression of transcription factors Snail and TWIST1 through the MAPK signaling pathway and inhibiting epithelial-mesenchymal transition." (PMID 35865337, 2022). "Two of the six transcriptional regulators (RUNX2 and TWIST1) are deregulated in other lung diseases (LD) (i.e., idiopathic pulmonary fibrosis (IPF) and pulmonary arterial hypertension (PAH))." (PMID 36551878, 2022). "We studied the effects of PNS on the MAPK signaling pathway and related transcription factors Snail and TWIST1 to explore the deep mechanism of PNS on Pulmonary fibrosis." (PMID 35865337, 2022). "Twist1 contributes to the age- and angiogenesis-related diseases, including pulmonary fibrosis, diabetes, COPD, cancer, and atherosclerosis." (PMID 33764901, 2021). "Other transcription factors and co-factors (e.g., TFII-I, GATA2, YAP1) that sense mechanical forces interact with Twist1, control angiogenesis, and contribute to age-related lung diseases (e.g., pulmonary fibrosis, pulmonary hypertension)." (PMID 33764901, 2021). "It is reported that TWIST1 promotes inflammatory pathways, which leads to various pathological conditions such as atherosclerosis, nephropathy, and pulmonary fibrosis." (PMID 34660572, 2021). "A transcription factor, Twist1, contributes to the age- and angiogenesis-related diseases, including pulmonary fibrosis, diabetes, chronic obstructive pulmonary disease (COPD), cancer, and atherosclerosis." (PMID 33764901, 2021). "A transcription factor, Twist1, contributes to the pathogenesis of age- and angiogenesis-related diseases such as pulmonary fibrosis and atherosclerosis." (PMID 33764901, 2021). "The transcription factor Twist-related protein 1 (Twist1) is known to play a role in lung vascular permeability and dysfunction, pulmonary fibrosis, pulmonary edema, and lung angiogenesis." (PMID 33503992, 2021). "We have demonstrated that endothelial Twist1 contributes to the pathogenesis of pulmonary fibrosis in a bleomycin-induced mouse pulmonary fibrosis model." (PMID 32371931, 2020). "For example, mechanosensitive transcription factors (e.g., TFII-I, GATA2, TWIST1) control angiogenesis and EC integrity, and contribute to angiogenesis-related diseases (e.g., pulmonary fibrosis, pulmonary hypertension)." (PMID 31487690, 2019). "In addition, a recent study of idiopathic pulmonary fibrosis found that TWIST1 protein expression and open chromatin at TWIST1 binding sites were both elevated in myofibroblasts." (PMID 38139368, 2023). "Increased levels of TWIST1 contribute to pulmonary fibrosis and lung injury through Tie2 signaling." (PMID 34660572, 2021).
pulmonary fibrosis (continued). "TWIST1 is involved in obesity- and angiogenesis-associated diseases such as diabetes, chronic obstructive pulmonary disease (COPD), cancer, pulmonary fibrosis, and atherosclerosis." (PMID 34660572, 2021). "In recent years, the role of Twist1 in pulmonary fibrosis has begun to be revealed." (PMID 29314610, 2018). "Thus, EPB41L3 may inhibit the progression of EMT by interacting with Snail1, 2, and Twist1 in patients with pulmonary fibrosis." (PMID 37373330, 2023). "Susceptibility to CS-induced pulmonary fibrosis might be influenced by genetic variations in EMT-related genes, such as Snail Family Transcriptional Repressor 1 (SNAI1), Twist Family BHLH Transcription Factor 1 (TWIST1), and Zinc Finger E-Box Binding Homeobox 1 (ZEB1)." (PMID 37371940, 2023). "Therefore, regulating the expression of TWIST1 is a curative strategy for pulmonary fibrosis." (PMID 35865337, 2022). "Hence, the exact role of Twist1 in pulmonary fibrosis needs further study." (PMID 29314610, 2018). "Our findings suggest that PNS can effectively inhibit the migration of Snail and TWIST1 from the cytoplasm to the nucleus, preventing EMT and further treating pulmonary fibrosis." (PMID 35865337, 2022). "Taken together, our study shows that PNS can improve and treat pulmonary fibrosis by modulating EMT occurrence through MAPK and Snail/TWIST1 signaling pathways." (PMID 35865337, 2022). "Other mechanosensitive transcription factors and co-activators (e.g., TFII-I, GATA2, Twist1, YAP1) also control angiogenesis, and contribute to lung diseases (e.g., pulmonary fibrosis, pulmonary hypertension)." (PMID 30612120, 2019). "Taken together, ectopic expression of Snail and TWIST1 may be involved in reducing epithelial cells and increasing mesenchymal cells to induce EMT, ultimately leading to pulmonary fibrosis." (PMID 35865337, 2022).
renal fibrosis (23 papers, 2014 to 2025). A final common manifestation of a wide variety of chronic kidney diseases characterized by glomerulosclerosis and tubulointerstitial fibrosis. "The expression of Twist1 in macrophages was increased in renal specimens from patients with IgAN IV–V compared with those with IgAN II–III, possibly inferring an association between Twist1 expression and advanced renal fibrosis." (PMID 35182235, 2022). "In this study, we found for the first time that increased expression of Twist1 in macrophages was significantly associated with the severity of renal fibrosis in IgA nephropathy patients and mice with unilateral ureteral obstruction (UUO)." (PMID 35182235, 2022). "In this study, we characterized the effect of Twist1 on macrophage polarization and on the progression of renal fibrosis and investigated the underlying mechanisms." (PMID 35182235, 2022). "Twist1 is therefore functionally associated with renal fibrosis." (PMID 35664054, 2022). "Intriguingly, these cytokines were lower in Twist1-deficient M2 macrophages, suggesting that Twist1 modulates the expression of profibrotic cytokines that might lead to the development of renal fibrosis." (PMID 35182235, 2022). "In addition, several publications revealed that rhein improves renal fibrosis and is associated with the nuclear factor kappa B and Twist1 pathways." (PMID 36059935, 2022). "Additionally, Twist1 was shown to directly activate Gal3 transcription, and Gal3 upregulation recovered Twist1-mediated M2 macrophage polarization in Twist1 deficient macrophages, suggesting that Twist1/Gal3 signaling modulates macrophage plasticity and promotes renal fibrosis." (PMID 36909244, 2023). "While previous studies have identified TWIST1 as a regulator of PHOX1 in renal fibrosis, research on the regulation of PHOX1 in tumors remains limited, and our work uncovers a distinct epigenetic mechanism underlying PHOX1 activation in GC." (PMID 41315175, 2025). "Two previous studies showed that partial EMT of epithelial cells induced by Snail1 and Twist1 promotes inflammatory responses during renal fibrosis." (PMID 39913299, 2025). "Gal-3 is probably involved in renal fibrosis via the alternative polarization of macrophages toward M2, since Twist1 knock-out mice develop reduced renal fibrosis and Twist-1 is known to be a stimulator of Gal-3 expression." (PMID 39125698, 2024). "It has been shown that Twist1/Gal-3 signaling facilitates renal fibrosis through regulating M2 macrophage polarization." (PMID 38371379, 2024). "Collectively, rhein protects rats from renal fibrosis by regulating SirT1/STAT3/Twist1 pathway to promote Cpt1a-mediated fatty acid degradation." (PMID 35408745, 2022). "We previously demonstrated that Twist1 expression in renal tubular epithelial cells plays an important role in EMT in renal fibrosis." (PMID 35182235, 2022). "In conclusion, Twist1/galectin-3 signaling regulates macrophage plasticity (M2 phenotype) and promotes renal fibrosis." (PMID 35182235, 2022). "In this study, we demonstrated that rhein prevents renal fibrosis by promoting Cpt1a-mediated FAO through SirT1/STAT3/Twist1 pathway." (PMID 35408745, 2022). "The ablation of Twist1 in macrophages significantly alleviated renal fibrosis in the UUO mouse model by inhibiting macrophage chemotaxis and M2 polarization, confirming that Twsit1-mediated macrophage heterogeneity plays a key role in renal fibrosis." (PMID 35182235, 2022). "TWIST1 upregulates C3 that stimulates the expression of TGF-β1, which induces the EMT phenomenon to cause renal fibrosis." (PMID 36018840, 2022). "We detected that mice with conditional deletion of Twist1 in proximal PTCs (PT-Twist1-/-) were resistant to renal fibrosis." (PMID 35664054, 2022). "In renal fibrosis, Twist1 is a driving force of EMT in RTE cells by negatively regulating Cpt1a-mediated FAO." (PMID 35408745, 2022).
renal fibrosis (continued). "Ablation of Twist1 in macrophages markedly alleviated renal tubular injury and renal fibrosis in UUO mice, accompanied by a lower extent of macrophage infiltration and M2 polarization in the kidney." (PMID 35182235, 2022). "Here, we present that rhein upregulated Cpt1a-mediated FAO through the SirT1/STAT3/Twist1 pathway to improve renal fibrosis." (PMID 35408745, 2022). "We and others have demonstrated that Twist1 expression was elevated in renal tubular epithelial cells and is involved in an epithelial mesenchymal transition (EMT) program implicated in renal fibrosis." (PMID 35182235, 2022). "Twist1 regulates macrophage plasticity to promote renal fibrosis through galectin-3." (PMID 38371379, 2024). "Importantly, in a renal fibrosis mouse model, we found that Twist1 deletion in proximal tubules led to upregulation of PGC-1α expression and prevented defective mitochondrial FAO activation." (PMID 35664054, 2022). "It is possible that TWIST1 is also involved in the EMT phenomenon to induce renal fibrosis." (PMID 36018840, 2022). "In summary, these results indicate that Twist1 in macrophage may regulate macrophage transition to myofibroblast-like cells to promote renal fibrosis." (PMID 35182235, 2022). "Indeed, Twist1 expression in macrophages was positively correlated with severe renal fibrosis in patients with IgAN and renal fibrosis in mice after UUO." (PMID 35182235, 2022). "Nevertheless, it was still unknown whether Twist1 regulates the biological functions of matrix cells that influence renal fibrosis." (PMID 35182235, 2022). "Here, we provide evidence that increased Twist1 might be one of the mechanisms for the infiltration and functional heterogeneity of macrophages in renal fibrosis." (PMID 35182235, 2022). "Rhein can improve renal fibrosis by blocking SirT1/STAS3/Twist1/Cpt1a-depandent FAO dysfunction, which may also be one of the mechanisms for rhubarb drugs." (PMID 35408745, 2022). "It is likely that other Twist1 downstream targets might also be involved in Twist1-mediated macrophage polarization and renal fibrosis." (PMID 35182235, 2022). "The study provides evidence that Twist1 in macrophages may regulate macrophage plasticity and heterogeneity to promote renal fibrosis." (PMID 35182235, 2022). "In the unilateral ureteral obstruction (UUO)-induced renal fibrosis model, Twist1 deletion in PTCs inhibited the EMT process, maintained the integrity of cells, and restored cell proliferation and repair and regeneration of the kidney parenchyma, ultimately alleviating renal interstitial fibrosis." (PMID 35664054, 2022). "This study suggests that inhibiting Twist1 or its target galectin-3 could be a potential new therapeutic strategy to prevent or treat renal fibrosis." (PMID 35182235, 2022). "Whether Cpt1a reverses renal fibrosis through its interaction with Twist1 remains to be further studied." (PMID 35408745, 2022). "This led us to investigate whether transcription factor Twist1 expressed by renal macrophages may regulate macrophage plasticity and heterogeneity to promote renal fibrosis." (PMID 35182235, 2022). "We explored the mechanism of the contribution of Twist1-regulated M2 macrophages in renal fibrosis." (PMID 35182235, 2022). "Mechanistically, we found that Twist1 in macrophages might contribute to renal fibrosis through either the secretion of profibrotic growth factors or direct transition to myofibroblast-like cells." (PMID 35182235, 2022). "During renal fibrosis linked with ER stress, TGF-β acts as a major regulator in renal tubular epithelial cells through the PI3K/Akt, Notch signaling, and Wnt/β catenin pathways via transcriptional factors such as Zeb1, Snail, TWIST1." (PMID 34645789, 2021). "More recently, the role of Twist1 in renal fibrosis has drawn considerable attention." (PMID 29314610, 2018).